NID1 (nidogen 1)
Diseases named in the same sentence as NID1 in open-access papers (continued):
Sharing a sentence is not in itself a finding about the gene and the disease.
cancer (continued). "It was previously reported that NID1 plays a key role in multiple malignant tumors." (PMID 32357143, 2020). "With this report we show that endothelial cell derived nidogen-1 represses cancer cell migration." (PMID 30947697, 2019). "There are few reports with respect to the pathological role of NID1 in cancer progression." (PMID 28416770, 2017). "It would be interesting to test if reduced nidogen-1 expression occurs in premetastatic niches and could therefore prepare ease-of-entry for later incoming cancer cells and investigate if these effects only occur in some organs (e.g. lungs) and not others (e.g. kidney)." (PMID 41181108, 2025). "However, recombinant biglycan reduced cancer cell migration to a similar extent than nidogen-1." (PMID 30947697, 2019). "We identified several extracellular proteins as up‐regulated in invaded compared to noninvaded nerves (some of these were also seen in PNI compared to non‐PNI cancer), including laminins LAMA2, LAMB1, COL6A3, periostin (POST), nidogen 1 (NID1), and TNC." (PMID 30690892, 2019). "COL11A1, COL6A1, MMP2, NID1, and FLT4 have been shown to have a positive role in regulating motility and invasion of various cancer cells." (PMID 28555007, 2017). "Furthermore, NID1 may be involved in the defense against infiltration of cancer cells." (PMID 26663990, 2015). "We show that CpG islands of both NID1 and NID2 genes are aberrantly methylated in human cancer samples and cancer cell lines." (PMID 17328794, 2007). "Nidogen 1 (NID1), a component of the extracellular matrix and basement membrane, facilitates interactions with laminins, collagens, and proteoglycans, thereby activating EMT and regulating cancer cell polarization, migration, and invasion." (PMID 39937175, 2025). "Taken together, these findings suggest that nidogen-1 is highly expressed in CAFs but not in cancer cells." (PMID 41181108, 2025). "To confirm that nidogen-1 is expressed by αSMA positive cells and not 4T1 cancer cells, we injected H2B-GFP labelled 4T1 cells into αSMA::RPF transgenic mice." (PMID 41181108, 2025). "We have shown that many cancer cells, both epithelial originated and neural crest originated, do not express nidogen-1." (PMID 41181108, 2025). "Other authors have investigated the impact of NID1 in cancer suggesting a potential negative prognostic role but prospective data are lacking and, in the end, results are inconclusive." (PMID 36624406, 2023). "Some genes, which appeared to be virtually switched off in B4GALNT2-expressing cells, are involved in the basic properties of cancer cells, such as stemness (SOX2, ROR1), epithelial to mesenchymal transition (EMT) (NID1, ALX1), and growth (FAM110B, PEG10, MID2)." (PMID 32290493, 2020). "To assess whether nidogen-1 was exclusively expressed by endothelial cells, we tested its protein expression in confluent and subconfluent HUVECs and in SK-BR-3 and PC3 cancer cells." (PMID 30947697, 2019). "Four genes (SERPINB7, INHBA, GJA1, and NID1) have two isoforms that have significantly different expression between the cancer and non-oncogenic groups." (PMID 23594586, 2013). "We detected NID1 as a gene reactivated by treatment with the demethylating agent zebularine in the human cancer cell line MDA-MB-231 (data not shown)." (PMID 17328794, 2007). "Moreover, the tested cancer cells did not express nidogen-1 at levels comparable to HUVECs." (PMID 30947697, 2019). "Analysis of the results confirmed that nidogen-1 is expressed in CAFs but not in 4T1, HCmel12, and B16F10 cancer cells." (PMID 41181108, 2025). "The cleavage of nidogen-1 by PSA may lead to disruption of basement membrane structure and may facilitate cancer cell invasion, but our results suggest that PSA-generated nidogen-1 or galectin-3 fragments do not mediate the antiangiogenic function of PSA." (PMID 25237904, 2014).
gastrointestinal tumors (1 paper, 2007). "Here, we report that methylation of nidogen 1 and 2 promoters is responsible for loss of their gene expression and is frequent in human gastrointestinal tumors." (PMID 17328794, 2007). "We investigated the presence of aberrant methylation at the NID1 and NID2 promoters in primary gastrointestinal neoplasms." (PMID 17328794, 2007).
NID1 also shares sentences with these, for which no sentence is quoted: endothelial dysfunction (2 papers); gastric tumors (2); glioblastoma (2); rheumatoid arthritis (2); Aicardi-Goutières syndrome (1); arteriovenous malformation (1); asthma (1); cervical cancer (1); chordoma (1); COVID-19 (1); dry eye (1); glomerular disorder (1); glomerulonephritis (1); Graves disease (1); IgA nephropathy (1); infection (1); lupus nephritis (1); metastatic cancer (1); nasopharyngeal carcinoma (1); neural tube defect (1); nevus (1); oesophageal cancer (1); oral cavity squamous cell carcinoma (1); prostate tumors (1); psoriasis (1); pulmonary arterial hypertension (1); Retinal dystrophy (1); systemic vasculitis (1); type 1 diabetes (1).